LINC01056 (long independently transcribed non-coding RNA 1056)
Gene: Long non-coding RNA gene on chromosome 20 (63,038,011 to 63,053,863, forward strand). Ensembl gene ENSG00000237119.
Diseases named in the same sentence as LINC01056 in open-access papers:
LINC01056 is named in the same sentence as 2 diseases in open-access papers, as found by Europe PMC text mining. Sharing a sentence is not in itself a finding about the gene and the disease. The quoted sentences say what the papers report.
cancer (1 paper, 2017). A tumor composed of atypical neoplastic, often pleomorphic cells that invade other tissues. "In their results, 160 lncRNAs were found to be dysregulated in cancer, of which seven were found in our 658 lncRNA list (LOC645949, LINC00896, FAM99B, LINC00167, LINC01056, SND1-IT1, NCBP2-AS2)." (PMID 28415559, 2017).
tumours (1 paper, 2024). "At the end of the study, the livers were harvested, and Linc01056 knockdown was found to result in a larger tumour size and higher tumour weight in sorafenib-treated mice bearing HCC tumours." (PMID 38582885, 2024). "We found that the cytoplasmic expression of Linc01056 was significantly downregulated in HCC tumour tissue compared to non-tumour adjacent tissue, consistent with the data reported from two other HCC patient cohorts, GSE62232 and GSE76297." (PMID 38582885, 2024). "Significant downregulation of Linc01056 expression was observed in sorafenib-resistant HCC tumours compared to their sorafenib-sensitive counterparts." (PMID 38582885, 2024). "In our present study, we found that knockdown of Linc01056 in HCC cells led to a higher level of intracellular ATP, which could be a metabolic advantage that increases the ability of tumour cells to overcome the stress caused by sorafenib challenge." (PMID 38582885, 2024). "We observed that Linc01056 knockdown significantly reduced the in vivo tumour response to sorafenib treatment without a change in body weight, as indicated by the rate of tumour growth." (PMID 38582885, 2024). "Knockdown of Linc01056 reduced the sensitivity of HCC cells to sorafenib, suppressing apoptosis in vitro and promoting tumour growth in mice in vivo." (PMID 38582885, 2024). "Knockdown of Linc01056 attenuated the sensitivity of HCC cells to sorafenib treatment, thus resulting in sorafenib resistance in HCC tumours in vivo." (PMID 38582885, 2024). "Linc01056 was significantly upregulated upon short-term sorafenib challenge but was repressed in HCC cells with acquired sorafenib resistance in vitro and in vivo in tumours derived from these cells." (PMID 38582885, 2024). "To examine whether Linc01056 expression is suppressed in sorafenib-resistant HCC, we established in vivo-generated sorafenib-resistant HCC tumours according to our previous study." (PMID 38582885, 2024).